POU3F4 (POU class 3 homeobox 4)
Diseases named in the same sentence as POU3F4 in open-access papers:
POU3F4 is named in the same sentence as 39 diseases in open-access papers, as found by Europe PMC text mining. Sharing a sentence is not in itself a finding about the gene and the disease. The quoted sentences say what the papers report.
deafness (30 papers, 2006 to 2024). An inherited or acquired condition characterized by the complete loss of the ability to hear from one or both ears. "In mammals, Pou3f1 appears to be the key factor for neural fate promotion, while the only neural defect caused by the loss of Pou3f4 is deafness." (PMID 36831281, 2023). "Males are more often affected by POU3F4-related deafness due to its X-linked pattern of transmission, but female carriers have been reported as displaying a wide range of hearing loss phenotypes, with or without inner ear malformations." (PMID 37371790, 2023). "These cells expressed several causal genes for various deafness forms, including Eps8l2, Gjb2, Gjb6, Homer2, Coch, Clic5, Dcdc2a, Pou3f4, Col4a6, and Six1." (PMID 37339214, 2023). "The pathomechanism underlying POU3F4-related deafness and the corresponding transcriptional targets are largely uncharacterized." (PMID 36245926, 2022). "The results of this study suggest that POU4F3 is the most common TF gene to cause non-syndromic deafness, excluding POU3F4 associated with X-linked inherited deafness in IP type III." (PMID 36140227, 2022). "The POU3F4 gene is associated with DFNX2 deafness with the X-linked recessive inheritance, while the variant c.607_610del, p.(Gln203Glufs*37) detected in our patient is suggested to be pathogenic." (PMID 34062854, 2021). "Further familial evidence suggested that the deafness phenotypes caused by variant of the POU3F4 gene, characterized by progressive conductive and sensorineural hearing loss." (PMID 33860785, 2021). "In fact, deafness caused by POU3F4 mutation accounts for nearly 50% of all cases of X-linked non-syndromic HL." (PMID 30176854, 2018). "Firstly, in a t(X;1) carrier with hearing loss, a highly skewed X-inactivation pattern was observed and the der(X) breakpoint mapped ~87kb upstream an X-linked deafness gene namely POU3F4, thus suggesting an underlying long-range position effect mechanism." (PMID 30289920, 2018). "Mice lacking Pou3f4 also show abnormalities of specialized fibrocytes apposed to the bony cochlear wall, a dramatically reduced endolymph potential, and profound deafness, suggesting that loss of Pou3f4 disrupts cochlear fluid homeostasis." (PMID 25299585, 2014). "Thus, the marked decrease in endocochlear potential measured in Pou3f4‐deficient mice as well as the progressive nature of the deafness are likely to be due to the presumed degeneration of suprastrial SLFs." (PMID 37786584, 2022). "In our cohort, POU3F4 was the TF gene most commonly associated with non-syndromic deafness." (PMID 36140227, 2022). "Interestingly, in a large, multigenerational consanguineous family, we identified two separated variants in HGF and POU3F4, illustrating the complex genetic heterogeneity of deafness." (PMID 33976695, 2021). "Thus, we suggest that AAV7‐Pou3f4 transduction in newborn Pou3f4−/y mice could help to restore cochlear functions and properties, including a positive endocochlear potential, before hearing loss progresses to profound deafness." (PMID 37786584, 2022). "POU3F4-related deafness is characterized by a typical inner ear malformation, namely an incomplete partition of the cochlea type 3 (IP3), with or without an enlargement of the vestibular aqueduct (EVA)." (PMID 36245926, 2022). "It increased probe coverage density for 29 genes (full-length design for GJB2, SLC26A4, and POU3F4 genes) to facilitate Cap-CNV analysis and detection of deafness-associated genes in mitochondrial loop DNA." (PMID 36350814, 2022). "As summarized above, in this study, rare pathogenic variants were identified in four separate deafness-associated genes, TECTA, MYO7A, HGF, and POU3F4, which have distinct expression profiles and functions in the inner ear." (PMID 33976695, 2021).
deafness (continued). "In this study, we performed targeted NGS in three Pakistani consanguineous families and identified novel variants in TECTA and POU3F4 and previously reported variants in MYO7A and HGF as the pathogenic causes for prelingual, severe-to-profound deafness." (PMID 33976695, 2021). "Using a panel of 109 reported human deafness genes, we found that 6 of 12 patients with IP-III carried mutations in the POU3F4 coding region." (PMID 33860785, 2021). "Mutations in POU3F4/Pou3f4, the encoding of a transcription factor, and POU-domain protein cause deafness in humans and mice." (PMID 35069120, 2021). "The variants of TMC1, ESPN, POU3F4, MYH14, EYA1, and MR-RNR1 genes followed those from the top tier deafness genes in the order of frequency as a molecular etiology of severe-to-profound NSHL in Vietnamese." (PMID 30733538, 2019). "The genetic locus for this non-syndromic form of deafness (DFNX2, formerly DFN3; OMIM 304400) maps to Xq21.1 and is associated with mutations of coding or regulatory sequence for the POU3F4 gene." (PMID 25299585, 2014). "Mutations in nine deafness genes (COCH, KCNQ4, MYO7A, TECTA, CRYM, POU3F4, EYA1, mitochondrial tRNA(Lys) m.8296A>G, mitochondrial tRNA(Ser) m.7445A>G) were not identified in any patients." (PMID 22384008, 2012). "Mutations in the POU3F4 gene emerge as the principal pathogenic contributors to IP-III anomalies, primarily manifesting through inner ear potential irregularities leading to deafness." (PMID 38498189, 2024). "Thus, an AAV7‐mediated delivery of Pou3f4 complementary DNA (cDNA) in the spiral ligament of Pou3f4−/y mice represents an attractive strategy to prevent SLF degeneration and to restore normal cochlear functions before hearing loss progresses to profound deafness." (PMID 37786584, 2022). "Five prominent deafness-related genes, GJB2, SLC26A4, GJB6, POU3F4, and mtDNA 12S rRNA, were analyzed." (PMID 22389666, 2012). "A control group was selected from age- and sex-matched children with CI and no variants in POU3F4, but instead carrying pathogenic sequence alterations in the GJB2 gene, which is the most common genetic cause of non-syndromic deafness in Caucasian populations." (PMID 37371790, 2023). "The precise molecular pathophysiological mechanisms would be different between POU3F4- and POU4F3- related deafness in speculation of the different modes of inheritance (X-linked recessive vs autosomal dominant, respectively)." (PMID 24260153, 2013).
hearing loss (24 papers, 2012 to 2026). "POU3F4 exemplifies this limitation in X-linked hearing loss, where stringent genotype-phenotype correlations and localised mutational hotspots dominate the pathogenic landscape." (PMID 42214845, 2026). "We explored a possible genotype–phenotype correlation in our cohort, excluding patients with pathogenic biallelic c.35delG GJB2 variants and POU3F4 variants, which are known to lead to severe hearing loss phenotypes." (PMID 40121402, 2025). "In the present review, we summarize and discuss the genetic variants identified in the POU3F4 gene that have been associated with hearing loss." (PMID 37371790, 2023). "Earlier, Petrina and coauthors revealed the variant c.907C>T in the POU3F4 gene as a cause of X-linked hearing loss in a Nogai family from the Karachay–Cherkess Republic." (PMID 36743950, 2023). "Normothermia TTM upregulated 13 genes associated with hearing loss, including Loxhd1, Tecta, Zmiz1, Espn, Gjb2, Sesn3, Bdp1, Hg, Pax3, Rnls, Syne4, P2rx2, and Pou3f4." (PMID 38298897, 2023). "Loss of DNA binding and consequent lack of transcriptional activity are therefore the most likely molecular mechanisms underlying POU3F4-linked hearing loss." (PMID 37371790, 2023). "The identification and characterization of the transcriptional targets of POU3F4 is an essential step towards a better understanding of the pathomechanism of POU3F4-related hearing loss and the associated phenotypes." (PMID 37371790, 2023). "In patients with an IP-III, targeted Sanger sequencing of POU3F4 will most likely lead to a conclusive genetic diagnosis of hearing loss." (PMID 37371790, 2023). "Research on the transcriptional targets of POU3F4 in the ear and brain is in its early stages and is expected to greatly advance our understanding of the pathophysiology of POU3F4-linked hearing loss." (PMID 37371790, 2023). "X‐linked deafness type 2 (DFNX2, locus Xq21.1), caused by POU3F4 mutations, accounts for nearly 50% of all cases of X‐linked hearing loss." (PMID 37786584, 2022). "Frameshift truncation and extension mutations in the C-terminal of POU3F4 are reported to cause cytoplasmic localization and then proteasomal degradation due to structural abnormalities, leading to non-syndromic hearing loss." (PMID 33919129, 2021). "The molecular genetic research showed the association between X-linked hearing loss and mutations in POU3F4, providing the definitive diagnosis and genetic counseling for this family and further enriched pathogenic mutation spectrum of the POU3F4 gene." (PMID 32952548, 2020). "The aim of the present study was to screen for POU3F4 mutations in a group of 30 subjects with a suggestive clinical phenotype as well as a group (N = 1671–2018) of unselected hearing loss patients." (PMID 27941975, 2016). "POU3F4 gene defects have been implicated in patients with congenital stapes fixation and labyrinthine dysplasia associated with sensorineural hearing loss." (PMID 25126438, 2014). "Several reports have described POU3F4 mutations in patients with hearing loss and temporal bone abnormalities." (PMID 22389666, 2012). "The fact that motor impairments are reported in a number of cases in association with the hearing loss phenotype in patients with IP-III and pathogenic variants in POU3F4 allows for speculation on the possibility of a syndromic form of hearing loss." (PMID 37371790, 2023). "Additionally, the patient will require auditory monitoring based on a strong predisposition to hearing loss known to be associated with POU3F4 gene defects." (PMID 25126438, 2014). "POU3F4 is the gene most commonly associated with X-linked deafness (DFNX2, DFN3) and accounts for about 50% of the cases of X-linked non-syndromic hearing loss." (PMID 37371790, 2023). "For what concerns X-linked non-syndromic hearing loss, 5 genes have been identified so far: PRPS1, SMPX, AIFM1, COL4A6, and POU3F4." (PMID 37371790, 2023).
hearing loss (continued). "Consistently, a similar type of hearing loss has also been associated with many variants in TECTA, MYO7A, HGF, and POU3F4 in previous reports." (PMID 33976695, 2021). "Additionally, other genes such as the CEVA haplotype, FOXI1, KCNJ10, POU3F4, and possibly GJB2 are implicated in 50 %–60 % of cases of hearing loss and enlargement." (PMID 39481243, 2024). "The lack of a precise understanding of the POU3F4 transcriptional targets and their physiological function in the context of hearing loss further limits the identification of possible therapeutic targets." (PMID 37371790, 2023). "The deleted region harbors 12 OMIM genes, of which POU3F4, CHM, and ZNF711 might have contributed to the patient’s phenotype including hearing loss, poor vision, and intellectual disability." (PMID 28630650, 2017). "In this study, no EYA1, MYO7A, or POU3F4 gene mutations were detected in any of the 717 hearing loss patients." (PMID 27627659, 2016). "We performed a genetic screening of GJB2 gene (responsible for the major etiologies of hereditary hearing impairment among Romanians), GJB3, GJB6, POU3F4 and WFS1 genes." (PMID 33333757, 2020). "Interestingly, a large deletion involving CHM and the neighboring POU3F4 and ZNF711 genes has been previously identified in a CHM patient with hearing impairment and developmental disability." (PMID 34440285, 2021).
X-linked deafness (8 papers, 2015 to 2024). "Pathogenic sequence alterations in the POU3F4 gene, which encodes a transcription factor, are causative of the most common type of X-linked deafness (X-linked deafness type 3, DFN3, DFNX2)." (PMID 36245926, 2022). "SNHL due to x-linked deafness (DFNX2) by pathogenic variants in the POU3F4 gene were initially concealed by a consistent air-bone gap." (PMID 33919129, 2021). "The Pou3f4 gene encodes a transcription factor implicated in X-linked deafness (DNFX2) in humans." (PMID 38577978, 2024). "We will focus on the type of inner ear malformations commonly associated with defects in POU3F4 and on the possibility of a syndromic form of X-linked deafness, where defects in organs other than the auditory apparatus are reported in patients with pathogenic variants of POU3F4." (PMID 37371790, 2023). "Variants in the POU3F4 gene at the locus DFN3 are a major cause of X-linked deafness worldwide." (PMID 31131597, 2019).
X-linked deafness-2 (5 papers, 2014 to 2025). "Disruptions or mutations of the POU3F4 gene have been implicated in X-linked deafness-2 (DFNX2), also called conductive deafness with stapes fixation (DFN3)." (PMID 25126438, 2014). "Mutations in the POU3F4 gene cause X-linked deafness-2 (OMIM #304400, DFNX2), also known as conductive deafness with stapes fixation." (PMID 37108562, 2023).
ear malformation (3 papers, 2021 to 2022). "Incomplete partition type III (IP-III) is a relatively rare inner ear malformation that has been associated with a POU3F4 gene mutation." (PMID 33919129, 2021).
sensorineural hearing loss (3 papers, 2010 to 2022). "It is therefore conceivable that a defective imino acid transport resulting from reduction of expression SLC6A20 in the inner ear as a consequence of POU3F4 loss of function might lead to sensorineural hearing loss, similarly to what was observed in the context of SLC6A20 pathogenic gene variations." (PMID 36245926, 2022). "Mutations in the human POU3F4 coding unit leads to X-linked deafness type 3 (DFN3), characterized by conductive hearing loss and progressive sensorineural deafness." (PMID 21209840, 2010). "Mutations in another member of the POU family, the POU3F4 (Brn4) causes deafness type 3 (DFN3), characterized by a conductive hearing loss that results from stapes fixation and progressive sensorineural deafness." (PMID 21209840, 2010).
X-linked nonsyndromic deafness (3 papers, 2017 to 2025). "Pou3f4delJ mice are a model for human X-linked nonsyndromic deafness (DFN3) caused by mutations in the gene POU3F4, which is a transcription factor." (PMID 40674144, 2025). "Pou3f4 is a transcription factor that has been implicated in X-linked non-syndromic deafness." (PMID 29073148, 2017).
developmental delay (2 papers, 2014 to 2023). "Here we present an overview of the pathogenic gene variants of POU3F4 reported in the literature and discuss the associated clinical features, including hearing loss combined with additional phenotypes such as cognitive and motor developmental delays." (PMID 37371790, 2023).
non-syndromic hearing loss (2 papers, 2018 to 2021). "Many X-linked non-syndromic hearing loss (HL) cases are caused by various mutations in the POU domain class 3 transcription factor 4 (POU3F4) gene." (PMID 30176854, 2018). "To date, five X-linked genes have been found to be related to the etiology of non-syndromic hearing loss (NSHL): PRPS1 (DFNX1, OMIM:311850), POU3F4 (DFNX2, OMIM:300039), SMPX (DFNX4, OMIM:300226), AIFM1 (DFNX5, OMIM:300169) and COL4A6 (DFNX6, OMIM:303631)." (PMID 33860785, 2021).
acute myeloid leukemia (1 paper, 2022). Acute myeloid leukemia (AML) is a group of neoplasms arising from precursor cells committed to the myeloid cell-line differentiation. "The DELs upstream of POU3F4 were also located downstream of SH3BGRL, which was reported to play a role in gastric cancer, acute myeloid leukemia and breast cancer." (PMID 35189936, 2022).
CHARGE syndrome (1 paper, 2014). CHARGE syndrome is a multiple congenital anomaly syndrome characterized by the variable combination of multiple anomalies, mainly Coloboma; Choanal atresia/stenosis; Cranial nerve dysfunction; Characteristic ear anomalies (known as the major 4 C's). "Furthermore, enlarged vestibular aqueduct, incomplete partition type III, lateral canal dysplasia as a manifestation of CHARGE syndrome was a very highly penetrant feature of mutations in SLC26A4, POU3F4, and CHD7, respectively in this population." (PMID 25373420, 2014).
choroideremia (1 paper, 2015). Choroideremia (CHM) is an X-linked chorioretinal dystrophy characterized by progressive degeneration of the choroid, retinal pigment epithelium (RPE) and retina. "POU3F4 has a proven role in hearing loss and inner ear malformations, ZNF711 has been associated with simple ID and CHM with the choroideremia." (PMID 25821518, 2015).
otospondylomegaepiphyseal dysplasia (1 paper, 2024). An inborn error of cartilage collagen formation characterized by sensorineural hearing loss, enlarged epiphyses, skeletal dysplasia with disproportionately short limbs, vertebral body anomalies and a characteristic facies. "In the catalog (CD−M7), Pou3f4, Homer2, and Col11a2 were associated with NSHL, Snai2 with Waardenburg syndrome, Lars2 with Perrault syndrome, and Col11a2 with otospondylomegaepiphyseal dysplasia." (PMID 39684410, 2024).
neurodevelopmental disorder (2 papers, 2022). A behavioral and cognitive disorder with onset during the developmental period that involves impaired or aberrant development of intellectual, motor, or social functions. "Mutations and deletions in the gene or upstream of the gene encoding the POU3F4 transcription factor cause X‐linked progressive deafness DFNX2 with inner ear malformations and additional neurodevelopmental disorders." (PMID 37786584, 2022). "Mutations and deletions in the gene or upstream of the gene encoding the POU3F4 transcription factor cause X‐linked progressive deafness DFNX2 and additional neurodevelopmental disorders in humans." (PMID 37786584, 2022). "Furthermore, a recent study showed that POU3F4 variants were associated with neurodevelopmental disorders, such as hyperactivity, concentration difficulties, poor phonological working memory, and slow language development, all of which may contribute to a negative CI outcome." (PMID 36140227, 2022).
tumor (1 paper, 2025). "Noting that POU3F4 and FGFBP3 have been linked to a neural stem cell (NSC) identity, we compared DAOY cells in co-culture with the DAOY tumor spheroid sample for expression of NSC markers." (PMID 39896075, 2025).
POU3F4 also shares sentences with these, for which no sentence is quoted: Hearing impairment (3 papers); Intellectual disability (2); adenocarcinoma (1); Alport syndrome (1); branchio-oto-renal syndrome (1); breast carcinoma (1); cleft palate (1); developmental disability (1); epidermolysis bullosa (1); fragile X syndrome (1); gastric cancer (1); hearing disorder (1); Jervell and Lange-Nielsen syndrome (1); Kennedy disease (1); meningitis (1); Menkes syndrome (1); Mohr-Tranebjaerg syndrome (1); Norrie disease (1); Pendred syndrome (1); Perrault syndrome (1); spinal muscular atrophy (1); Usher syndrome (1); Waardenburg syndrome (1); X-linked intellectual disability (1).